HIF1A (hypoxia inducible factor 1 subunit alpha)
Diseases named in the same sentence as HIF1A in open-access papers (continued):
Sharing a sentence is not in itself a finding about the gene and the disease.
pancreatic cancer (continued). "A specific inhibitor of TGFß receptor kinase -SB-431542, or HIF-1α -IDF-11774 were shown to efficiently suppress tumor-promoting effects in pancreatic cancer cells and colorectal carcinoma, respectively." (PMID 37853467, 2023). "First, C4orf47 is a direct gene target of HIF-1α in pancreatic cancer cells and is up-regulated under hypoxic conditions." (PMID 36741255, 2023). "In pancreatic cancer, a natural small molecule, astaxanthin, acts via the HIF-1α/STAT3 axis to mediate RRM2, regulating the gemcitabine-induced EMT phenotype." (PMID 36678539, 2022). "Hypoxia-induced circ_0000977 has been identified to modulate immune escape of pancreatic cancer cells via the miR-153/HIF-1α axis." (PMID 35915091, 2022). "The orally active HIF-1α translation inhibitor PX-478 sensitized pancreatic cancer cells to radiation, both in vitro and in vivo." (PMID 35053572, 2022). "The functionalized liposomes reduced the tumor by twofold more when compared with unmodified liposomes, suggesting the potential of gemcitabine/HIF1α-siRNA-loaded GE-11-modified liposomes in pancreatic cancer treatment." (PMID 35456655, 2022). "In the TME of pancreatic cancer, hypoxia induces the overexpression of circ0000977, increases the expression of HIF1A and ADAM10, enables tumor cells to avoid immune surveillance and suppresses the lethal effect of NK cells on pancreatic cancer cells." (PMID 36238299, 2022). "Pancreatic cancer is a solid tumor, and hypoxia is also a common tumor microenvironment, resulting in the upregulation of HIF-1α." (PMID 35819532, 2022). "Further experimental results showed that P4HA1 can increase the stability of HIF1α to form a positive feedback loop, which is a critical regulator in glycolysis and oncogenic activities of pancreatic cancer." (PMID 35651786, 2022). "The expression of HIF-1α in tumor cells under normoxia resists cytotoxic T lymphocytes (CTLs) and induces immune escape of pancreatic cancer cells from NK cells through the shedding of MICA, which interacts with NK-activating receptor (NKG2D)." (PMID 35283421, 2022). "Quinones: The expression of GLUT1, HK2, and PFK1 is suppressed and the level of HIF-1α is lowered by emodin and rhein in human pancreatic cancer cells (MiaPaCa2)." (PMID 36339566, 2022). "Given that the hypoxic tumor microenvironment (TME) supports the growth and metastasis of pancreatic cancer cells, inactivation of hypoxia-inducible factor-1α (HIF-1α) with CRISPR/Cas9 is suggested as another rational therapeutic approach." (PMID 35508982, 2022). "The HIF-1α-dependent upregulation of autophagy and cell survival has been postulated in prostate cancer, pancreatic cancer, and colorectal cancer (CRC)." (PMID 36551540, 2022). "Gemcitabine is a potential antitumoral agent used as a first-line drug for pancreatic cancer treatment, whereas HIF1α-siRNA can downregulate the HIF1-α, a heterodimer related to tumor cells’ survival in hypoxia conditions." (PMID 35456655, 2022). "In a study, checked the effectiveness of oncolytic H-1 parvovirus in pancreatic cancer cells with HIF-1α overexpression." (PMID 35686109, 2022). "Hypoxic exosomes obtained from pancreatic tumor cells trigger macrophages to the M2 phenotype in an HIF1a or HIF2a-dependent manner, leading to facilitated migration, invasion, and epithelial–mesenchymal transition of pancreatic cancer cells." (PMID 36233088, 2022). "CircZNF91 was encapsulated and transmitted to normoxic pancreatic cancer cells through hypoxic exosomes, eventually enhancing the stability of HIF-1α and leading to glycolysis and chemoresistance of normoxic pancreatic cancer cells." (PMID 35444652, 2022). "Another study showed that tamoxifen reduces HIF1A expression in stromal cells by suppressing myosin-dependent contraction and matrix stiffening in pancreatic cancer." (PMID 35205794, 2022).
pancreatic cancer (continued). "In lung and pancreatic cancer and in head-and-neck squamous carcinoma, HIF-1α has been suggested to induce the expression of Slug through the binding of HRE in its promoter." (PMID 35745656, 2022). "Targeting the HIF-1α signaling pathway is effective in the treatment of solid tumors, such as pancreatic cancer." (PMID 36212414, 2022). "In another study, reported that H-1 oncolytic parvovirus along with HIF-1α inhibitor resulted in improved antitumor response with increased apoptosis in pancreatic cancer." (PMID 35686109, 2022). "Previous studies have suggested that tamoxifen treatment reduces HIF1A levels by suppressing mechanotransduction in pancreatic cancer." (PMID 35205794, 2022). "LncRNA PCED1B-AS1 promotes proliferation, invasion and EMT of pancreatic cancer cells by regulating the miR-411-3p/HIF-1α axis in pancreatic cancer by inducing the upregulation of HIF-1α." (PMID 35819532, 2022). "LncRNA FEZF1-AS1 can act as an oncogene to enhance pancreatic cancer cell proliferation and invasion through the miR-142/HIF-1α axis under hypoxic conditions." (PMID 35819532, 2022). "For instance, increased circ0000977 expression induced by hypoxia promotes the immune escape of the pancreatic cancer cells mediated by HIF-1α (hypoxia inducible factor-1 alpha)." (PMID 35186039, 2022). "Lee and colleagues showed that the deletion of HIF-1α induced B cell infiltration and accelerated the progression of pancreatic cancer." (PMID 35565420, 2022). "Phosphorylated signal transducer and activator of transcription 3 (STAT3) is also a hypoxia-responsive nuclear transcription factor that has been shown to act synergistically with HIF-1α to regulate angiogenesis under hypoxia in pancreatic cancer cells." (PMID 36408139, 2022). "In another study of primary human pancreatic tumors and KC mouse model crossed to Hif1αfl/fl the hypoxia inducible factor-1α (HIF1α) was found to be highly expressed during the pre-invasive stage of PDAC and deletion of HIF1α accelerated PDAC development." (PMID 35359944, 2022). "Though TQ is reported to induce cell death in renal cell carcinoma and pancreatic cancers via inhibiting HIF1α and pyruvate kinase M2 (PKM2)-mediated glycolysis, further studies are warranted to elucidate the underlying mechanism/s using more cell models." (PMID 35216429, 2022). "An animal model of pancreatic cancer with hyperglycemia showed that HIF-1α is abundantly expressed in cancer cells." (PMID 36011045, 2022). "HIF-1α also promotes pancreatic cancer cells to secrete TGF-β, a critical modulator of inflammation and an important chemoattractant for Treg recruitment into tumors." (PMID 35493517, 2022). "It was confirmed that YEATS2 was the target gene of hypoxia-inducible factor 1α (HIF1α) and abundantly expressed in pancreatic cancer tissues, which was related to poor prognosis." (PMID 34587874, 2021). "HGF/MET signaling promotes CSC properties by inducing YAP nuclear translocation and HIF-1α stabilization in pancreas cancer." (PMID 34439392, 2021). "Previous studies have shown that high HIF-1α expression levels decreased the sensitivity to gemcitabine, which has been used in pancreatic cancer treatment." (PMID 33830713, 2021). "Given the co-occurrence of mutant KRAS with high HIF-1α and high galectin-3 levels in pancreatic cancer, our results suggest an application of Hsp90 inhibitors in this cancer type." (PMID 33672199, 2021). "According to a recent study, increased expression of DCLK1 assists in hypoxia-induced stemness in pancreatic tumors, initiated by the cooperation between HIF-1α and histone lysine demethylase 3A (KDM3A)." (PMID 34453639, 2021). "Emerging evidence indicated that hypoxia-induced HIF-1α stabilization and assessment contributes to progression and metastasis of pancreatic cancer." (PMID 34881179, 2021). "We developed a novel anti-HIF-1α nanobody and demonstrated the function of VHH212-encoding adenovirus in a preclinical murine model of PANC-1 pancreatic cancer." (PMID 33830713, 2021).
pancreatic cancer (continued). "In pancreatic cancer, HIF-1α recruits histone deacetylase 1 (HDAC1) to the promoter of miR-548an, which transcriptionally suppresses miR-548an expression and subsequently upregulates vimentin, which facilitates pancreatic tumorigenesis." (PMID 34884541, 2021). "Gemcitabine-resistant pancreatic cancer cells increased expression of HIF-1α by upregulating MUC1 expression, along with increased glycolytic phenotype and dependence on glucose." (PMID 34976805, 2021). "A direct correlation between hypoxia and CD133 expression has been established; CD133 + cells co-localize to the hypoxic areas within the pancreatic tumors and show enhanced hypoxia-inducible factor-1α (HIF-1α) activity." (PMID 34453639, 2021). "It was reported that HIF-1α activation promotes the expansion of CD133-positive CSCs in brain and pancreatic cancers, whereas HIF-1α deletion decreases leukemia stem cell capacity." (PMID 33681231, 2021). "Simultaneously, there were two clinical trials in progress using digoxin as a chemical inhibitor of HIF-1α in pancreatic cancer." (PMID 33830713, 2021). "Obese conditions induce hypoxia and activate hypoxia-inducible factor 1-alpha (HIF1a), which was shown to directly activate Ob-R in pancreatic cancer cells." (PMID 33668583, 2021). "MiR‐210 inhibits the expression of HOXA9 to activate the NF‐κB signaling, induces EMT, and reduces the sensitivity of pancreatic cancer cells to gemcitabine induced by HIF1A under hypoxia." (PMID 33939301, 2021). "The hypoxic microenvironment of pancreatic tumors stabilizes HIF-1α, which promotes glucose metabolism." (PMID 34976805, 2021). "In the present study, we demonstrate for the first time that incubating KLM-1 pancreatic cancer cells with oxLDL, under normoxic conditions, leads to HIF-1α stabilization." (PMID 34475995, 2021). "YAP1 has been widely correlated with asthma, and also known to influence disease progression by mediating HIF-1α in liver cancer and pancreatic cancer." (PMID 33980319, 2021). "It was investigated to inhibit the expression of HIF-1α in human pancreatic cancer cells by emodin and rhein if any inhibitory effect alleviates cancer cachexia." (PMID 34073059, 2021). "As a result, emodin and rhein reduce pancreatic cancer cell growth and the expression of HIF-1α and alleviate cancer cachexia in cancer cells." (PMID 34073059, 2021). "For instance, in the hypoxic pancreatic cancer microenvironment, HIF-1α induces gemcitabine (GEM) resistance." (PMID 33672261, 2021). "MiR-210-3p is a predominant hypoxia HIF1α-inducible microRNA in a broad spectrum of cancer types, including pancreatic cancer." (PMID 34944818, 2021). "Emodin and rhein reduced HIF-1α expression in MiaPaCa2 and four other human pancreatic cancer cell lines." (PMID 34073059, 2021). "RAGE-mediated HIF-1α activation occurs during hypoxia through the modulation of NF-κB—RAGE—Kirsten Rat Sarcoma viral oncogene homologue (KRAS)—HIF1α signaling in pancreatic cancer cells." (PMID 33466626, 2021). "We aimed to develop a novel anti-HIF-1α intrabody to decrease gemcitabine resistance in pancreatic cancer patients." (PMID 33830713, 2021). "In pancreatic cancer, HIF-1a induced miR-21 overexpression, preventing tumor cells from apoptosis in an oxygen-deficient environment." (PMID 32587480, 2020). "HIF-1α was overexpressed in pancreatic cancer, and a knockdown of HIF-1α suppressed the metastasis of pancreatic cancer." (PMID 32437450, 2020). "Collectively, these results suggested that c-Myc regulated the HIF-1α/SDF-1/CXCR4 pathway in pancreatic cancer cells to enhance the antitumor effect of bufalin." (PMID 32362830, 2020).
pancreatic cancer (continued). "VEGF-A role in pancreatic cancer progression also influences tumor cells glucose metabolism: it enhances glycolysis via HIF-1α upregulation and NRP-1 co-receptor involvement." (PMID 32085654, 2020). "Downregulation of c-Myc enhanced the antitumor activity of bufalin in pancreatic cancer cells by suppressing the HIF-1α/SDF-1/CXCR4 pathway." (PMID 32362830, 2020). "Studies indicate HIF-1α promotes the proliferation of pancreatic cancer cells through various mechanisms." (PMID 32587480, 2020). "HIF-1α depletion also increased p21 and p27 levels and attenuated cell proliferation in the pancreatic cancer cells, similar to Mint3 depletion." (PMID 32826949, 2020). "It has been demonstrated that high expression of HIF-1α can increase resistance of pancreatic tumor cells to the current first line chemotherapeutic gemcitabine and that knock down of HIF-1α combined with gemcitabine leads to significant synergistic effects." (PMID 33322697, 2020). "In line with this, elevated levels of HIF-1α and HH were found in pancreatic tumors and identified as markers of decreased patient survival." (PMID 32707920, 2020). "In pancreatic cancer, gemcitabine treatment activated NF-κB and HIF-1α via ROS-mediated activation of ERK1/2 and Akt, upregulating chemokine receptor 4 (CXCR4) expression and contributing to gemcitabine resistance by CXCR4/chemokine 12 (CXCL12) signaling." (PMID 32587480, 2020). "HIF-1α target genes, TKT and CTPS1, regulating pyrimidine synthesis are associated with primary and metastatic pancreatic cancer tissues." (PMID 32707920, 2020). "Prolyl hydroxylase domain 3 (PHD3), a rate-limiting enzyme regulating HIF-1α degradation, improves radiotherapy efficacy through inhibiting p-EGFR/HIF-1α signaling in pancreatic cancer." (PMID 32587480, 2020). "Several studies revealed that HIF-1α and NF-κB expression were increased in pancreatic cancer tissues and there was a positive feedback regulation between them, resulting in chemoresistance partly." (PMID 32587480, 2020). "Mucin1 is a type I transmembrane protein which is widely expressed in pancreatic cancer tissues and regulates anabolic glucose metabolism in a HIF-1α-dependent manner in pancreatic cancer." (PMID 32587480, 2020). "HIF1α is a major regulator of cellular adaption to hypoxia and is enriched in most pancreatic cancer tissues." (PMID 32322663, 2020). "A large number of studies demonstrated HIF-1α-mediated pancreatic cancer cells EMT, invasion and metastasis in hypoxia." (PMID 32587480, 2020). "HIF-1α is in a complex signaling network and regulates the biological characteristics of pancreatic cancer cells in diverse manners." (PMID 32587480, 2020). "As expected, by comparing its expression level between pancreatic cancer patient tumor and adjacent normal tissues, we found HIF1α to be significantly upregulated in the patient tumors." (PMID 32322663, 2020). "CD133 is one of surface molecules of pancreatic cancer stem cells, and its expression is increased in a HIF-1α-dependent manner in hypoxia." (PMID 32587480, 2020). "The study indicated STIM1 expression was upregulated, accompanied by HIF-1α overexpression in pancreatic cancer tissues." (PMID 32587480, 2020). "In pancreatic cancer, HIF-1α and ADAM10, a disintegrin and metalloproteinase domain 10 (ADAM10) are highly expressed and are negatively regulated by miR-153." (PMID 32587480, 2020). "The axis of circ-0000977/miR-153 can mediate HIF1α-induced immune escape of pancreatic cancer cells through targeting HIF1α/ADAM10." (PMID 31937318, 2020). "In searching for the underlying molecular effectors of H-1-2, we discovered that HIF1α and AGR2 mRNA were upregulated in tumor tissues of pancreatic cancer patients, both of which were previously implicated in the tumorigenesis of pancreatic cancer." (PMID 32322663, 2020).
pancreatic cancer (continued). "Hypoxia induced factor 1α (HIF-1α) is one of the main regulators of cell survival under hypoxic conditions and has been found to play a central role in tumor progression of pancreatic cancers, making it an interesting therapeutic target." (PMID 33322697, 2020). "miR-142 inhibits pancreatic cancer cell proliferation and invasion, partly by targeting HIF-1α at its binding site." (PMID 33317198, 2020). "Numbers of studies revealed high expression of HIF-1α markedly enhanced the anti-apoptotic capacity of pancreatic cancer cells." (PMID 32587480, 2020). "Increasing studies explore the roles of HIF-1α in pancreatic cancer and pancreas embryonic development." (PMID 32587480, 2020). "Meanwhile, HIF-1α was significantly highly expressed in head and neck squamous cell carcinoma and pancreatic cancer tissues." (PMID 33154192, 2020). "Intracellular expression of the HIF-1α VHH significantly enhanced gemcitabine cytotoxicity in pancreatic tumor cell lines, making it an interesting candidate for further therapeutic exploration." (PMID 33322697, 2020). "Our manuscript integrates acting mechanisms of HIF-1α to provide a comprehensive perspective of the role of HIF-1α in pancreatic cancer, showing theoretical principle for the targeted therapy of pancreatic cancer." (PMID 32587480, 2020). "On the contrary, under hypoxic conditions, when HIF-1α is activated and translocated into the nucleus, an enhanced miRNA-21 expression has a promoting effect on pancreatic cancer cell proliferation." (PMID 33113836, 2020). "Numerous studies revealed the central role of HIF-1α in the carcinogenesis and progression of pancreatic cancer." (PMID 32587480, 2020). "For instance, in pancreatic cancer cells under hypoxia, circ-0000977 can pass circ-0000977-miR-153-Hypoxia-inducible factor 1-α (HIF1α) axis to regulate HIF1α -mediated immune escape." (PMID 32467668, 2020). "In line with this, McDonald and colleagues showed that K-ras knockout pancreatic cancer cells reduced the protein level of HIF-1α, CAIX, and glycolysis in response to hypoxia." (PMID 32707920, 2020). "Recent studies in pancreatic cancer published by multiple groups have shown that high expression of HIF1α under hypoxia promoted CSC-like features in pancreatic cancer cells by inducing the CSC marker expression, chemoresistance and EMT phenotype." (PMID 33096662, 2020). "Among the tested EMT-related proteins, Mint3 depletion decreased Slug levels in pancreatic cancer cells in a HIF-1α- and SKP2-dependent manner." (PMID 32826949, 2020). "In the context of this study, H-1-2 exerts its beneficial role against pancreatic cancer by targeting hypoxia/HIF1α, supporting HIF1α as a promising therapeutic target in pancreatic cancer treatments." (PMID 32322663, 2020). "MTA2′s association with HIF-1α was previously shown in pancreatic cancer, as MTA2 deacetylases HIF-1α and consequently increases HIF-1α stability." (PMID 32640630, 2020). "Decreased Rho GTPase-activating protein 4 (ARHGAP4) facilitates aerobic glycolysis of pancreatic cancer through activating HIF-1α pathway and upregulating M2 isoform of pyruvate kinase (PKM2) expression." (PMID 32587480, 2020). "A recent report has shown that a hypoxia condition and subsequent elevated HIF-1α levels increase fibrogenesis, leading to stimulate the formation of collagen I and fibronectin by fibroblasts in pancreatic cancer cells." (PMID 31968685, 2020). "In pancreatic cancer cells, miR‐142 was found to suppress cell proliferation and invasion partly by targeting hypoxia‐inducible factor 1α (HIF‐1α), an oncogene." (PMID 32652747, 2020). "Hypoxia-inducible factor-1alpha (HIF-1α) was reported to be an important transcriptional factor in pancreatic cancer under a hypoxic condition 3,27." (PMID 32127956, 2020). "The study suggested hypoxia-induced HIF-1α contributed to chemoresistance and radiotherapy resistance in pancreatic cancer." (PMID 32587480, 2020).